IL11 (interleukin 11)
Diseases named in the same sentence as IL11 in open-access papers (continued):
Sharing a sentence is not in itself a finding about the gene and the disease.
cancer (continued). "IL-11 is a multifunctional cytokine with effects on hepatocytes, B-cells, macrophages, osteoclasts, cardiac myocytes and fibroblast hematopoietic cells including functions in cardiac regeneration and fibrosis, colon regeneration, bone metabolism and cancer." (PMID 34927050, 2021). "Using the human cancer database, we find that the expression of some genes with enriched expression in IL-11+ fibroblasts is also elevated in human CRC and that high expression of a set of these genes is correlated with reduced recurrence-free survival in CRC patients." (PMID 33863879, 2021). "IL-11 plays a vital role in tumorigenesis and cancer progression." (PMID 34149927, 2021). "IL-11 facilitated cancer cell chemoresistance via IL-11R/STAT3 signalling." (PMID 33671869, 2021). "IL-11 in turn activates GP130/STAT3 in cancer cells to initiate metastasis." (PMID 36046433, 2021). "IL‐11 could increase the tumorigenic abilities of cells including the survival of cells or origin, proliferation of cancer cells, and survival of metastatic cells of distant organs." (PMID 32869505, 2020). "Therefore, there is a mechanistic link between the gut microbiota and cancer metastasis through the IL-11/circRNA/miRNA axis." (PMID 32686598, 2020). "Based on the current knowledge of the biological properties of IL‐11 and its role in cancer, IL‐11 signaling inhibition might be a new therapeutic approach for cancer treatment." (PMID 32869505, 2020). "Furthermore, analysis of gut microbiota by deep sequencing combined with animal models and fecal transplantation identified a critical role of gut microbiota in the regulation of cancer progression and metastasis through IL-11/circRNA/miRNA/SOX9 axis." (PMID 32686598, 2020). "IL-11 signaling drives several cancer hallmarks including cell survival, metastasis, and invasion." (PMID 32765502, 2020). "However, only a few studies on targeting IL-11 or its receptor-αin cancers in pre-clinical models have been published so far." (PMID 30736824, 2019). "IL-11 is a member of the IL-6-type cytokine family and may provide a link between inflammation and cancer." (PMID 31852428, 2019). "Akin to our findings with IL11‐Mutein therapy, tumors from bazedoxifene‐treated mice had reduced expression of the pro‐survival protein Bcl‐xL, of the proliferative marker cyclin D1 and the cancer cell‐specific mitosis marker survivin." (PMID 30885958, 2019). "Notably, induction of both IL-11 and LIF in response to TGF-β stimulation of cancer-associated fibroblasts is thought to promote tumor progression." (PMID 31156640, 2019). "A functional IL-11Rα subunit might trigger signal transduction by IL-11 in human cancer cells cultured under hypoxic conditions." (PMID 30197757, 2018). "Although the oncogenic roles of STAT3 are well known, the roles of IL-11 in cancer are relatively unknown." (PMID 30086773, 2018). "IL11 is now also emerging as an attractive therapeutic target for cancer." (PMID 28186993, 2017). "IL-11 transmits signals through its unique receptor, IL-11Rα, which couples with the common receptor subunit GP130 to activate the downstream STAT3 signaling pathway, a pathway that is closely associated with cancer pathogenesis." (PMID 29100303, 2017). "The current study demonstrates that IL-11 could be a potential therapeutic target for cancer metastasis." (PMID 27487122, 2016). "IL-11 is shown to be a key IL-6 family cytokine during gastrointestinal cancers, which is involved into progression of breast cancer, osteosarcoma, and many other cancers." (PMID 27916836, 2016). "In this paper, we report a crucial role of IL-11 in the functional differentiation and immunosuppressive mechanisms of MDSCs, which may serve as a possible target for cancer immunotherapy." (PMID 28781374, 2015). "Interleukin-11 (IL-11) promotes osteoclast formation and inhibits osteoblast activity and may thus be one factor involved in cancer-induced bone destruction." (PMID 26082068, 2012).
cancer (continued). "IL11 is predominantly restricted to cancer epithelium and not cancer associated stromal fibroblasts, suggesting that in the cancer stroma, factors other than IL11 regulate pSTAT3." (PMID 20553623, 2010). "Notably, IL-11 has been reported to trigger JAK/STAT signaling in regulation of human cancer." (PMID 37153732, 2023). "Interestingly, the effect of CM on the level of GPR84 was significantly reversed in the presence of IL-11 NAb, indicating that blocking the endogenous IL-11 secreted by cancer cells could regulate the expression of GPR84." (PMID 36593458, 2023). "However, the specific role of IL-11 in HGSOC remains unclear as IL-11 expression is low in this specific cancer." (PMID 35326569, 2022). "Various inflammatory biomarkers have been discussed in cancer studies as they have been linked to advanced cancer stages, resistance to immunotherapy, and poor prognosis: tumor necrosis factorα (TNF-α), interferon-γ (IFN-γ), and interleukin (IL)-1, IL-6, IL-8, IL-10, IL-11, and IL-17." (PMID 36499628, 2022). "Cytokines—i.e., IL-6, IL-8, IL-11, IL-27, IL-31—are small immunological proteins important in autocrine, paracrine, and endocrine signaling processes that influence inflammation, cell growth and proliferation, cell and matrix interactions, and disease progression in cancer." (PMID 35326569, 2022). "Thus, CAF-dependent IL-11 resistance mechanism may be of potential relevance in cancers of distinct origin." (PMID 33553157, 2020). "Removal of IL11 abrogated the growth competitiveness of YTHDF2-deficient SMMC7721 cells, while a SERPINE2 deficit attenuated the proangiogenic capacity of SMMC7721 cells, highlighting that IL11 and SERPINE2 are key targets of YTHDF2 in cancer-promoting inflammation." (PMID 31735169, 2019). "Therefore, our data suggested that the activation of PI3K and its downstream effector AKT by CUL1-induced CXCL8 and IL11 may play a role in cancer metastasis." (PMID 30578411, 2018). "Multiple other recombinant cytokines have already been approved for treatment of patients; IL-2 for cancer, several IFNα derivatives for cancer and viral infections, IL-11 thrombocytopenia induced by chemotherapy, IFNβ for multiple sclerosis and IFNγ for osteoporosis and cancer." (PMID 30622524, 2018). "Interleukin-11 is accompanied by its transmembrane receptor IL-11 receptor-alpha (IL-11Rα) and stimulates the proliferation of the breast neoplastic cells with the simultaneous growth of the primary cancer cells and the migration of the cancer cells into distant organs." (PMID 30648081, 2018). "Thus, IL-11-mediated regulation in functional differentiation of MDSCs may serve as a possible target for cancer immunotherapy." (PMID 28781374, 2015). "Given the critical roles of MDSCs in immunosuppression, our elucidation of the effector functions in IL-11-induced MDSCs has implications in the rational design of strategies for enhancing antitumor immune responses and development of new efficient treatments for cancer patients." (PMID 28781374, 2015). "Extensive research indicates that IL-11 and its receptor IL11RA are involved in crucial processes such as cell proliferation, differentiation, invasion, and metastasis in various cancers, significantly influencing tumorigenesis and progression." (PMID 40755754, 2025). "IL11, a member of the IL6 family, is a critical lynchpin between inflammation and cancer and is involved in inflammation and immune responses." (PMID 41590789, 2025). "Together with our findings, these observations suggest that cancer cells can exploit the normal process of EMT to migrate, invade, and metastasise using IL-11 signalling." (PMID 38248304, 2024). "Beyond IL-6, other members of the IL-6 cytokine family, such as IL-11, leukemia inhibitory factor (LIF), and oncostatin M (OSM), also play critical roles in the interplay between inflammation and cancer." (PMID 39421736, 2024).
cancer (continued). "CAFs assert their pivotal role within this vicious cycle, actively shaping an inflamed neoplastic niche where IL-6, IL-11, LIF, and CXCL5 orchestrate an inflammatory phenotype that fuels cancer progression." (PMID 39609411, 2024). "A pivotal aspect of our research was the elucidation of the IL-11/JAK1/STAT4/CBP signaling axis and its role in the upregulation of c-MYC, marking a significant progression in cancer biology." (PMID 38429845, 2024). "Secreted inflammatory cytokines in cancer cells, including IL-22, IL-6, IL-8, IL-4, IL-1β, HGF, IGF-1, EGF, G-CSF, TNF-α, VEGF, and IL-11, can confer the promotion of chemo- and radioresistance." (PMID 38140352, 2023). "IL-11 and its receptor, interleukin-11 receptor α (IL-11Rα) activate STAT3 signaling, which correlates with poor patient prognosis in most human cancers." (PMID 37240247, 2023). "BMMs were stimulated by four common components secreted by cancer cells as reported by previous studies, including EGF, IL-11, CTGF and PTHrP." (PMID 36593458, 2023). "IL-11-expressing fibroblasts and IL-11-ERK signaling in fibroblasts have been demonstrated to play pivotal roles in cancer and Ssc." (PMID 34804029, 2021). "Overall, the role of IL-6, IL-11 as well as of other interleukins, has been observed in MDR cancer cells; the clinical attempts to block their effects for therapeutic intervention have been described in a recent review." (PMID 34503172, 2021). "Among the paracrine pro-osteoclastogenic factors produced by cancer cells, RANKL, PTHrP, IL-11, and VEGF have particular relevance." (PMID 34439218, 2021). "STAT3, highly active in more than 50% of BCs, has been described as a key signalling orchestrator of many of the cancer-promoting effects exerted by IL6, but also IL11, LIF and OSM." (PMID 34834425, 2021). "IL-6 enhances cancer cell migration and EMT by activating STAT3 and IL-11 to facilitate resistance to chemotherapeutic drugs." (PMID 34063828, 2021). "Accumulating evidence suggests that TGFβ-stimulated CAFs increase the secretion of IL-6 and IL-11, which trigger GP130/STAT3 signaling in cancer cells and thus promote cancer metastasis and progression." (PMID 32972405, 2020). "Among them, IL-6 and IL-11 are secreted interleukins activating STAT-3-dependent survival and spreading of metastatic CRC cancer cells." (PMID 33553157, 2020). "Several researchers have found that IL11, another member of the IL6 family, can also activate JAK/STAT3 pathway in some cancer types 34-36." (PMID 33042272, 2020). "Precisely, these genes intersected for 21 candidate targets, among which IL11 and SERPINE2 were most relevant to cancer-promoting inflammation." (PMID 31735169, 2019). "Like IL-6, IL-11 can drive a STAT3-mediated regenerative program in epithelial cells, a function that promotes malignancy in cancers of the intestine, stomach, and mammary gland." (PMID 31156640, 2019). "To confirm that STAT3 signalling was activated in epidural ADSCs in response to paracrine secretion from cancer cells, we evaluated STAT3 phosphorylation in ADSCs after the addition of recombinant IL-6, IL-11 and LIF by western blot." (PMID 31196220, 2019). "Lastly, lncRNA-ATB activates the autocrine induction of IL-11 by binding to IL-11, and then activates STAT3 signaling to promote cancer cell colonization." (PMID 29692736, 2018). "Gene expression analysis by microarray demonstrated that MDR1A deficiency shaped the inflammatory response towards an anti-tumorigenic microenvironment by downregulating genes known to be important mediators of cancer progression (PTGS2 (COX2), EREG, IL-11)." (PMID 28686677, 2017). "At the same time, lncRNA-ATB upregulates interleukin-11 (IL-11) and activates IL-11/STAT3 (signal transducer and activator of transcription 3) signaling, which enables cancer cell colonization." (PMID 26989421, 2016).
cancer (continued). "Our data on knockdown and overexpression of SET7/9 demonstrate that SET7/9 suppressed CXCL2, IL-11 and three MMP genes in GC cells, which were shown to promote not only cancer cell motility and invasion but also metastasis." (PMID 26701885, 2016). "This study elucidates the prometastatic role played by IL-11 in ATC metastasis and indicates it as a potential target for the treatment of cancer metastasis." (PMID 27487122, 2016). "Our study revealed the critical role of IL-11 in crosstalk between the LMO2 highly expressed stromal cells and their adjacent cancer cells." (PMID 27028859, 2016). "In HEC-1A and Ishikawa carcinoma cells, there was an upregulation of SOCS3 protein following the addition of 100 ng/ml IL11 compared to respective controls." (PMID 20553623, 2010). "Furthermore, cancer cells disrupt the bone tissue by secreting osteolytic factors such as RANKL and IL-11, as well as releasing growth factors such as TGF-β, creating a self-perpetuating malignant cycle." (PMID 40224177, 2025). "The immunological role of IL11 + CAF in cancer is not clear, but highly expressed genes, including IL-6 cytokine family (IL6, IL11, OSM) are associated with immunotherapy resistance." (PMID 39757146, 2025). "In comparison, IL11 + CAF subtype are more inflammatory and found within cancers of the GI tract." (PMID 39757146, 2025). "Additionally, upregulated m6A-modified RNA AC026356.1 enhances cancer progression by binding IGF2BP1, stabilizing IL11 mRNA, and activating IL11/STAT3 signaling." (PMID 40034695, 2025). "Importantly, we showed that BZA is the first drug to concurrently inhibit both IL-6 and IL-11 signalling and suppress STAT3 activation in cancer cells." (PMID 38600086, 2024). "IL11 and IL18 are cytokines involved in hematopoiesis, cancer metastasis, and inflammation." (PMID 39484639, 2024). "In human cancer and primary cells, sgp130Fc inhibited IL6, IL11, OSM and CT1 cis-signalling." (PMID 38338642, 2024). "Although most research into STAT3 activation and downstream signalling has mainly been studied in the context of IL-6 stimulation, recent studies have shown an important role for IL-11 in STAT3 activation, especially in the initiation and progression of cancer." (PMID 38248304, 2024). "The gp130 family members, IL-11, IL-6, OSM, and LIF (upregulated in the LM) potentially impact skeletal muscle wasting by inducing the STAT3 signaling pathway in the preclinical model of cancer cachexia." (PMID 36774484, 2023). "Interestingly, the induction by TGFβ of IL11, a cytokine of the IL6/GP130 family involved in multiple cancer hallmarks, including cell migration and invasion, is greatly enhanced by decitabine." (PMID 34571856, 2021). "IL-11 induces Signal transducer and activator of transcription 3 (STAT3) phosphorylation and increases the expression of anti-apoptotic protein Bcl-2 and Survivin in cancer cells." (PMID 34503172, 2021). "While therapies targeting IL6-like cytokines such as IL11, OSM and CNTF are at different stages of development for the treatment of a range of diseases, only the IL11R-targeted agent BMTP-11 is being developed for its potential use in cancer treatment." (PMID 34834425, 2021). "Additionally, IL‐6 and IL‐11 activate STAT3 signalling, which works with NF‐κB to promote cancer development." (PMID 32347623, 2020). "Cancer cells originating from the breast can form typical osteolytic metastases in the BM by secreting parathyroid hormone-related protein (PTHRP), tumor necrosis factor-α (TNFα), interleukin 6 (IL-6) and/or interleukin 11(IL-11)." (PMID 31817646, 2019). "Interestingly, in the function of migration of cancer cells, we found two significantly downregulated cytokine genes CXCL8 and IL11, and the network diagram showed that reduced CXCL8 and IL11 expression inhibited cell migration." (PMID 30578411, 2018). "Furthermore, IL-11 induced STAT3 phosphorylation and increased anti-apoptotic protein Bcl-2 and Survivin expression in cancer cells." (PMID 27922075, 2016).
cancer (continued). "Meanwhile, IL-11 secreted from CAF could decrease cisplatin-induced apoptosis and promote cancer cells chemoresistance." (PMID 27922075, 2016). "Furthermore, it was also observed that IL-11 induced STAT3 phosphorylation and increased anti-apoptotic protein Bcl-2 and Survivin expression in cancer cells." (PMID 27922075, 2016). "STAT3 protein abundance was not affected at any IL11 concentration tested in all carcinoma cell lines." (PMID 20553623, 2010). "In non-carcinoma HES cells, SOCS3 protein increased after addition of IL11 from 1-500 ng/ml." (PMID 20553623, 2010). "Transcription factors such as STAT3 and NF-κB enhance IL11 transcription under inflammatory conditions, while cooperation with ERK signaling regulates processes including cell cycle progression, differentiation, and immune evasion in pathologies such as cancer and tissue injury." (PMID 41487426, 2025). "However, once cancer is established, the role of H. pylori-induced IL-11 is no longer the major factor for cancer progression." (PMID 40462044, 2025). "Moreover, the xenograft tumors created from the cancer cells treated with SP showed a higher level of pro-inflammatory cytokines (IL-4β, IL-6, IL-8, IL-11, IL-12, TNF-α, and transforming growth factor β [TGF-β]) compared with those generated from cancer cells treated with PBS." (PMID 36685035, 2023). "Thus, IL11-stimulated fibroblasts are primed to release IL33 when damaged to activate IL33 pathways in neighboring IL1RL1-expressing fibroblasts and other cells, which include immune cells in cancers." (PMID 36012165, 2022). "However, our understanding of how IL-11 impacts the initiation and progression cancers is still limited and no agent inhibiting IL-11 is currently approved for the treatment of solid cancers." (PMID 35844493, 2022). "Interleukin (IL)-6 family cytokines, such as IL-6 and IL-11, are defined by the shared use of the gp130 receptor for the downstream activation of STAT3 signaling and the activation of genes which contribute to the “hallmarks of cancer”, including proliferation, survival, invasion and metastasis." (PMID 35053592, 2022). "Furthermore, in patients with a broad spectrum of cancers, those with detectable serum IL11 had worse survivability compared to those without." (PMID 35883698, 2022). "Although the relationship between TGFβ /IL-11 signaling was explored mainly in CAFs, the effects of IL-11 on mechanisms of immune evasion during cancer metastasis have not yet been demonstrated in any cancer context." (PMID 35053592, 2022). "Further, in the absence of IL-11 (or its receptor) mice were protected from cancer development." (PMID 36591258, 2022). "Given that IL-11 Mutein does not show adverse effects on platelet numbers and it is well tolerated, it was suggested its potential use in clinical therapy also in other cancer types." (PMID 34201209, 2021). "However, we can speculate that IL‐6, IL‐11, and LIF secreted by PC may be responsible for some of them, as they have well‐known roles in cancer." (PMID 32767843, 2020). "Apart from previous reports demonstrating that IL-11 can also activate protein kinase/extracellular signal-regulated kinase (ERK), or the phsophotidylinositol-3 kinase (PI3K) pathways, the STAT3 pathway has been identified as a main pathway activated by chemokines in cancer cells." (PMID 27922075, 2016). "IL-11 may not be involved in homing of the disseminated cancer cells to bone." (PMID 37199584, 2023). "IL-11 and LIF seem to promote EMP in some cancer types, even if the mechanisms are not as thoroughly described." (PMID 34361105, 2021). "In YTHDF2-deficient cells, re-expression of wild-type YTHDF2 but not the catalytically inactive mutant offset the acquired cancer-promoting inflammatory phenotypes, and reduced both phosphorylation of STAT3 and stabilization of IL11 and SERPINE2 mRNAs." (PMID 31735169, 2019).